FGF2 (fibroblast growth factor 2)
Diseases named in the same sentence as FGF2 in open-access papers (continued):
Sharing a sentence is not in itself a finding about the gene and the disease.
leukemia (continued). "In vitro analysis was discrepant, suggesting that FGF2 treatment decreased the supportive properties of stromal cells, while FGF2-treated osteoblasts were somewhat more supportive of leukemia cell growth." (PMID 27481339, 2016). "In BM, FGF2 treatment increased total numbers of leukemia cells including the number of CD34+ positive leukemia cells." (PMID 27481339, 2016). "We first tested the effects of FGF2 on the proliferation of stromal cells (MS-5 and S-17), osteoblast cells (7F2), and leukemia cells (NCO2, Meg-A2 and TRL-01)." (PMID 27481339, 2016). "The results above suggested that FGF2 induces indirect effects from osteoblasts that are supportive of leukemia cell growth." (PMID 27481339, 2016). "We describe a novel role of FGF2 as a modulator of osteoblast and mesenchymal stromal cell function, and provide evidence for involvement of FGF2 in leukemia pathogenesis." (PMID 27481339, 2016). "An increase in the number of leukemia cells induced by FGF2 was coupled with the increased bone marrow endosteal region: osteoblasts." (PMID 27481339, 2016). "Both the spleen size and the number of leukemia cells in mice treated with Ara-C alone, and mice treated with Ara-C plus FGF2 treatment, were reduced compared to control mice." (PMID 27481339, 2016). "The cell density within the marrow cavity in FGF2/Ara-C treated mice was higher than that from mice treated with Ara-C alone (top and 2nd row), which was due to the increased number of leukemia cells (confirmed by CD45 staining, 3rd and bottom row)." (PMID 27481339, 2016). "BM sections from FGF2-treated mice had thickened bone trabeculae and increased numbers of leukemia cells compared to controls." (PMID 27481339, 2016). "We found that FGF2 treatment attenuated the viability of human TRL-01 stromal-dependent leukemia cells." (PMID 27481339, 2016). "Thus, the autophagosome formation inhibition-mediated activation of AIM2 inflammasome can also synergize with a molecular-targeted drug, FLT3 inhibitor, to induce irreversible differentiation in leukemia cells with FLT3-ITD even in the presence of FGF2." (PMID 38466568, 2024). "However, after addition of BGJ398 or FGF2 knockdown, the expression of phosphorylation of PI3K/AKT/mTOR proteins were significantly reduced, indicating that FGF2/FGFR2 combination activated PI3K/AKT/mTOR pathway in leukaemia cells." (PMID 36333298, 2022). "FGF2 induces leukemia stem cell expansion in MLL1-rearranged AML." (PMID 32467231, 2020). "Likewise, Fgf2 -/- mice transplanted with retroviral BCR-ABL leukemia survive significantly longer than their +/+ counterparts when treated with TKI." (PMID 30720426, 2019). "This suggests that taking advantage of drugs that prevent bone marrow stromal cells from releasing FGF2 in exosomes might improve treatments for leukemia." (PMID 30720426, 2019). "The leukemia cells then use FGF2 to survive the effects of the kinase inhibitors." (PMID 30720426, 2019). "Fgf2 -/- mice survive significantly longer with TKI therapy in a murine BCR-ABL leukemia model." (PMID 30720426, 2019). "We next evaluated the effects of FGF2 on leukemia cells in vivo." (PMID 27481339, 2016). "Here, we examined the effects of FGF2 on the leukemia microenvironment." (PMID 27481339, 2016). "In our report, FGF2 had little proliferative effect on stromal cells and leukemia cells." (PMID 27481339, 2016). "A previous study using a 42-plex human cytokine array to analyze the serum of NSG mice engrafted with Nalm6-GFP leukemia cells reported high levels of PDX-intrinsic PDGF-AA and FLT-3 L as well as lower levels of FGF-2, VEGF-A, and TNFα." (PMID 36860657, 2023). "Activation of FGF2/FGFR1 signaling in bone marrow stromal cells promoted the secretion of FGF2/ FGFR1-laden exosomes, which were internalized by leukemia cells and contributed to their resistance to tyrosine kinase inhibitors." (PMID 36320056, 2022).
leukemia (continued). "Two ways were used to block the interaction between FGF2 and FGFR2: one way used shRNA to knockdown FGF2 in MSCs, the other way was FGFR inhibitor BGJ398 to competitively combined with FGFR2 in leukaemia cells." (PMID 36333298, 2022). "Treatment of leukemia cells with the PD173074 inhibitor, which binds the ATP pocket of FGFR2, prevents FGF2-mediated nuclear entry of pFGFR2 and, consequently, also transcriptional activation of MLL-AF4 target genes." (PMID 33924850, 2021). "We found that fibroblast growth factor 2 (FGF2) expression is increased in marrow stromal cells during tyrosine kinase inhibitor (TKI) therapy and protects leukemia cells." (PMID 30720426, 2019). "Here, we demonstrate that fibroblast growth factor 2 (FGF2) from bone marrow stromal cells is secreted in exosomes, which are subsequently endocytosed by leukemia cells, and protect leukemia cells from tyrosine kinase inhibitors (TKIs)." (PMID 30720426, 2019). "Interestingly, the spleen size and the number of leukemia cells in mice treated with Ara-C plus FGF2 tended to be lower compared to mice treated with Ara-C alone, which may be reflecting the in vitro results that FGF2 lowered the supportive properties of stromal cells toward leukemia cells." (PMID 27481339, 2016). "Ara-C treatment significantly reduced total numbers of leukemia cells and CD34+ positive leukemia cells, which was partially alleviated by the addition of FGF2." (PMID 27481339, 2016). "In bone marrow, FGF2 treatment increased total numbers of leukemia cells, including CD34+ positive leukemia cells." (PMID 27481339, 2016). "We next evaluated the effect of FGF2 treatment on the ability of MS-5, S-17 and 7F2 cells to support human TRL-01 stromal-dependent leukemia cells in culture." (PMID 27481339, 2016). "Conversely, FGF2 increased the proliferation of osteoblasts via FGFR1 IIIc, but its effects on osteoblast support of leukemia cell growth were limited." (PMID 27481339, 2016). "Ara-C treatment significantly reduced total numbers of leukemia cells, including CD34+ positive cells, which was partially alleviated by the addition of FGF2." (PMID 27481339, 2016). "After GO analysis of the seventy-four genes, six secreted cytokines related to cell cycle, proliferation and apoptosis including CSF2, CTF1, FGF2, IGF2, HGF and LIF were selected for PCR verification and FGF2 was confirmed to be significantly up-regulated in leukaemia mice derived MSCs." (PMID 36333298, 2022). "The human stromal cell line HS-5 expresses abundant FGF2, in addition to other soluble cytokines such as IL-5, IL-8 and HGF, and conditioned media (CM) from HS-5 is highly protective of leukemia cell lines." (PMID 30720426, 2019). "ECVs from PD173074-treated +/+ stroma or -/- stroma were not as protective, suggesting that Fgf2 +/+ stroma more effectively protects BCR-ABL leukemia cells from the effects of kinase inhibition through secretion of protective exosomes." (PMID 30720426, 2019). "RNA sequence results revealed that T-ALL derived MSCs secreted fibroblast growth factor 2 (FGF2), which combined with fibroblast growth factor receptor 2 (FGFR2) on leukaemia cells, resulting in activation of PI3K/AKT/mTOR signalling pathway in leukaemia cells." (PMID 36333298, 2022). "It was not clear how the FGF2 signal reaches the leukemia cells from the bone marrow stromal cells." (PMID 30720426, 2019). "We next treated a human leukemia mouse model with Ara-C with/without systemic FGF2 administration." (PMID 27481339, 2016). "In addition, mice whose bone marrow stromal cells could not produce FGF2 survived leukemia for longer than mice whose stromal cells provided protective FGF2 in exosomes to leukemia cells." (PMID 30720426, 2019). "Interestingly, FGF2 did not promote leukemia cell survival in Ara-C treated spleen." (PMID 27481339, 2016). "We next evaluated the effects of FGF2 on human NCO2 and Meg-A2 stromal-independent leukemia cells, which did not require supportive cells to propagate." (PMID 27481339, 2016).
bladder cancer (25 papers, 2002 to 2024). "A possible explanation for poor prognosis of FGF-2 expressing bladder cancers is the association with epithelial to mesenchymal transition (EMT), high proliferation, low mutation load and high expression of CTLA-4, PD-1 and PD-L1, thus being more sensitive to immune checkpoint inhibition." (PMID 28978000, 2017). "Given that high FGF-2 is an indicator of poor prognosis in bladder cancer, we asked whether FGF-2 expression may also be associated with immune checkpoint activation." (PMID 28515962, 2017). "Intriguingly, another work elucidated that FGF2 can increase enhancer of zeste homolog 2 (EZH2) expression by activating KDM2B in bladder cancer cells." (PMID 35177106, 2022). "More importantly, it has been detected in a prior study that FGF2 is capable of upregulating EZH2 in bladder cancer cells, which was partially consistent with our result." (PMID 35177106, 2022). "By TCGA analysis, we show that FGF-2 expression levels reversely and significantly correlated with survival advantages in breast, ovarian, and bladder cancers." (PMID 32709869, 2020). "In the HT1376 bladder cancer cell line, transduction of FGF2 cDNA also led to resistance to cisplatin." (PMID 30838090, 2019). "To address the potential contribution of these pathways to the biology of FGF-2-expressing bladder carcinomas, we searched publicly available genomics resources of invasive bladder cancer." (PMID 28515962, 2017). "The same analyses also revealed that FGF-2 correlates negatively with the expression, mutation and copy number variations of FGFR-3, all of which are associated with noninvasive bladder carcinomas." (PMID 28515962, 2017). "The cancer genome atlas (TCGA) data showing a correlation between KDM2B and EZH2 expression and Oncomine data, showing a correlation between KDM2B and tumor progression, strongly support the role of the FGF-2/KDM2B/miR-101/EZH2 pathway in bladder cancer." (PMID 28515962, 2017). "The preceding data identify FGF-2-expressing bladder carcinomas as a tumor subtype that is prone to EMT and is characterized by an invasive phenotype and poor prognosis." (PMID 28515962, 2017). "Further analyses of publicly available databases, revealed that FGF-2-expressing bladder carcinomas carry fewer genetic alterations and they tend to express high levels of CTLA-4, PD-1 and PD-L1, which suggests immune blockade by checkpoint activation." (PMID 28515962, 2017). "In summary, in this report we attempted an integration of data from publicly available databases, with our own experimental data, to explain the invasiveness and poor prognosis of FGF-2-expressing bladder carcinomas." (PMID 28515962, 2017). "In conclusion, our data confirm the involvement of high VEGFA and OPN levels in bladder cancer, as well as an important role for FGF2 and RHOC in this disease." (PMID 22895562, 2012). "During the early stages of tumor growth, FGF2 expression has been reported to play an important role in the regulation of angiogenesis, tumorigenicity and subsequent metastasis of human bladder cancer." (PMID 22895562, 2012). "We also found that high FGF2 levels exhibited a trend towards a correlation with worse patient survival (both overall and cancer-specific) and in the ROC curve, FGF2 exhibited a very good specificity for distinguishing bladder cancer from the normal tissue." (PMID 22895562, 2012). "Significantly increased FGF2 protein levels have previously been reported in bladder cancer by a number of studies, and its expression has been positively correlated with tumor stage and grade." (PMID 22895562, 2012). "During the early stages of tumor growth, FGF2 expression has been shown to play an important role in the regulation of angiogenesis, tumorigenicity and subsequent metastases of human bladder cancer." (PMID 22895562, 2012).
bladder cancer (continued). "VEGFA was the most sensitive (81.8%) factor and FGF2 the most specific (76.6%) one, for distinguishing bladder cancer patients from the control samples, with an AUC of 0.751 (95% CI, 0.674–0.817) and 0.742 (95% CI, 0.664–0.810), respectively." (PMID 22895562, 2012). "Regarding growth factor receptor genes, treatment with DOX increased some of these genes, such as ErbB2, ErbB4 and FGF2 in the tumors, which are up-regulated in bladder cancers and responsible for disease progression." (PMID 22824624, 2012). "At the early stage of tumor growth, FGF2 expression plays an important role in the regulation of angiogenesis, tumorigenicity and subsequent metastases of human bladder cancer." (PMID 21483670, 2011). "EMT, enhanced proliferation and immune checkpoint activation combined, may be responsible for the poor prognosis of FGF-2-expressing bladder carcinomas." (PMID 28515962, 2017). "Our prior studies suggested at least two molecular mechanisms that may contribute to the invasiveness of FGF-2-expressing bladder carcinomas." (PMID 28515962, 2017). "Given the importance of the FGF-2/KDM2B-EZH2/miR-101/EZH2 axis in bladder cancer, we hypothesize that there will be clinical utility to the therapeutic targeting of this pathway." (PMID 28515962, 2017). "FGF-2 also increases the invasive potential of bladder cancer cell lines." (PMID 21941546, 2011). "Interestingly, it has been reported that an anti-idiotypic strategy mimics the biological activity of FGF-2, inhibiting the progression of an experimental bladder cancer." (PMID 21042580, 2010). "However, further experiments should be performed to clarify the precise role of FGF-2 in response to BCG in bladder cancer." (PMID 21042580, 2010). "Moreover, FGF2 overexpression is conducive to bladder cancer cell migration and angiogenesis." (PMID 38764020, 2024). "Notably, bladder cancer expressing FGF-2 has also been identified as a tumor subtype prone to EMT, which may be related to the induction of KDM2B and EZH2 expression by FGF-2." (PMID 36966334, 2023). "In bladder cancer, FGF2 was significantly increased in chemo-resistant bladder cell lines, stimulating endothelial cell migration, growth and tube formation by producing FGF2, and thus playing an important role in the development of a cisplatin-resistant phenotype." (PMID 28978000, 2017). "To address this question, we examined the correlation between FGF-2 and FGFR-3 expression or FGF-2 expression and FGFR-3 genetic alterations in a set of 129 bladder carcinomas in the TCGA database for which curated sequence data were available." (PMID 28515962, 2017). "In vitro, MMP-1 production by bladder cancer cell lines can be stimulated by EGF; FGF-2 has also been shown to have an important regulatory role." (PMID 21941546, 2011). "Of note, the FGF2 levels were significantly higher in the metastatic vs. the non-metastatic bladder cancers (P=0.0097)." (PMID 22895562, 2012).
non-small cell lung carcinoma (25 papers, 2011 to 2025). A group of at least three distinct histological types of lung cancer, including non-small cell squamous cell carcinoma, adenocarcinoma, and large cell carcinoma. "Donnem and colleagues showed that high FGF2 expression in non-small-cell lung cancer (NSCLC) is associated with poor five-year survival." (PMID 27677589, 2016). "Previous studies have found that ace-miR-152 inhibits the proliferation and invasion of non-small cell lung cancer (NSCLC) cells by inhibiting fibroblast growth factor 2 (FGF2)." (PMID 40004485, 2025). "FGF2 knockdown in non-small cell lung cancer impedes cell proliferation, colony formation, migration, and invasion." (PMID 39091947, 2024). "For example, in breast and non-small cell lung carcinomas, FGF2 and FGF9 are expressed and activate their respective FGFRs in the same cells." (PMID 34830836, 2021). "For example, FGF-2-FGFR-1 activation through an autocrine loop was found as a mechanism of acquired resistance in non-small cell lung cancer (NSLC) to EGFR-tyrosine kinase inhibitor gefitinib." (PMID 32599808, 2020). "MiR-646 is involved in inhibiting proliferation and metastasis of non-small cell lung cancer by binding to FGF2 and CCND2." (PMID 32669977, 2020). "We have previously found FGF2 and the co-expressions of FGF2 & PDGF-B and FGF2 & VEGFR-3 to be poor independent prognosticators in an unselected large non-small cell lung cancer cohort." (PMID 21733164, 2011). "Interestingly, as both genes were overexpressed in poorly differentiated cell lines, FGF2/FGFR1 activation in non-small-cell lung cancer has been proposed as an important EGFR-TKI-resistance-acquisition mechanism." (PMID 32517019, 2020). "In addition, gefitinib sensitivity was also restored in non-small cell lung cancer cells when FGF2 and FGFR1 were inhibited via siRNA and treatment with a small molecule inhibitor, PD173074, suggesting FGFR activation as a potential mechanism of acquired resistance to EGFR-TKs." (PMID 34830836, 2021). "The hazard ratio for progression-free survival of ALK-TKIs increased in patients with ALK fusion-positive non-small cell lung cancer with FGFR1- and FGF2-high mRNA expression at baseline." (PMID 37880373, 2023). "In afatinib-resistant non-small cell lung cancer cells, overexpression of FGFR1 and FGF2 played a role in overcoming cell survival by compensating the loss of the estrogen growth factor receptor (EGFR)-driven signalling pathway." (PMID 34830836, 2021).
Cerebral ischemia (24 papers, 2008 to 2024). Restriction of arterial blood supply to the brain associated with insufficient oxygenation to support the metabolic requirements of the tissue. "The proliferation of neural progenitor cells occurs after cerebral ischemia by administration of Egf and Fgf2." (PMID 37763262, 2023). "The protective effect of FGF2 has been investigated in several disease conditions, such as cerebral ischemia injury and wound healing." (PMID 32266254, 2020). "There have been a number of attempts to develop neuroprotectants for brain ischemia, such as FGF-2, a brain-derived neurotrophic factor that has been tested for its ability to rescue neurons from ischemic cell death." (PMID 25237906, 2014). "FGF-2 was found to improve sensorimotor deficits and to reduce infarct size following cerebral ischemia in adult rats, and neutralizing antibodies to FGF-2 blocks recovery from motor cortex lesions." (PMID 24098645, 2013). "FGF2 also promote remyelination in cerebral ischemia models, bFGF exerted a protective effect on myelin by increasing the myelin thickness, the number of myelinated axons, and myelin basic protein expression in the hypoxia-ischemia (HI)-induced demyelinated neonatal rat corpus callosum." (PMID 29123467, 2017). "Particularly, several lines of evidence support that FGF2 activates PI3K/AKT as a classical pathway involved in neurogenesis and angiogenesis after cerebral ischemia." (PMID 37051111, 2023). "Growth factors including FGF-2, IGF-1, VEGF, and BDNF contribute to CNS development, they also are expressed in cortex after brain ischemia and involved in neuronal regeneration, remyelination and angiogenesis process." (PMID 29123467, 2017). "FGF2 and downstream PI3K/AKT signals provide the neuroprotective effect against cerebral ischemia." (PMID 37051111, 2023). "After cerebral ischemia, the increased expression of brain-derived neurotrophic factor (BDNF), platelet-derived growth factor-B (PDGF-B), transforming growth factor-beta (TGF-β), fibroblast growth factor 2 (FGF2), and VEGF, may promote both angiogenesis and axonal outgrowth." (PMID 35873557, 2022). "Other beneficial effects of FGF2 and IGF-1 involved in the subacute administration of zinc might be the stimulation of neuron survival and neurogenesis in the subventricular zone and the subgranular zone of dentate gyrus, since these events are triggered in adult rats following cerebral ischemia." (PMID 26355725, 2015).